UCA1 (urothelial cancer associated 1)
Diseases named in the same sentence as UCA1 in open-access papers (continued):
Sharing a sentence is not in itself a finding about the gene and the disease.
cancer (continued). "UCA1 is also known as a cancer upregulated drug resistant gene." (PMID 33777227, 2021). "Moreover, it was demonstrated that UCA1 is upregulated in hypoxia-resistant cancer cells generated by chronic hypoxia exposure, and that this lncRNA contributes to the augmentation of cell migration." (PMID 34298879, 2021). "UCA1 plays a role in drug resistance across several cancer entities." (PMID 32756406, 2020). "GAS8-AS1 and UCA1 were inversely correlated in cancer tissues." (PMID 32013985, 2020). "HOTAIR and UCA1 with multiple roles in drug resistance may offer big opportunities for targeted chemoresistance in cancer therapy." (PMID 31143372, 2019). "The UCA1 was found to be a predictor for poor prognosis in cancer development." (PMID 31596734, 2019). "Besides the oncogenic function, lncRNA UCA1 was also found to regulate drug resistance in multiple types of malignant tumors." (PMID 31695578, 2019). "UCA1 has been demonstrated correlated with clinical outcomes in various cancers." (PMID 30918102, 2019). "UCA1 has been extensively reported as a miRNA sponge in various cancer." (PMID 30940776, 2019). "These new approaches could indicate that the impairment of specific signaling pathways together with suppression of miRNAs (miR-21/miR-10b/miR-302) and/or lncRNA UCA1 in HA-CD44-activated cancer cells may be more effective than chemotherapy alone." (PMID 31293964, 2019). "UCA1 was found to promote chemo-resistance in various types of cancers." (PMID 31596734, 2019). "Third, UCA1 overexpression could promote cancer metastasis by activation of metastasis-related genes including GRK2/ERK-MMP9, EZH2/AKT, p21/E-cadherin, iASPP, KLF4-KRT6/13, FGFR1/ERK and ZEB1/2-FSCN1." (PMID 30918102, 2019). "UCA1 was found to play important roles in various types of cancers." (PMID 31596734, 2019). "Another meta-analysis explored that UCA1 might be a risk factor in predicting short OS and progression-free survival (PFS) in cancers, including CRC, NSCLC, GC, and OC." (PMID 31480503, 2019). "Moreover, we also identified that there was a significantly positive correlation between high UCA1 expression and short OS in cancer patients." (PMID 30918102, 2019). "For example, UCA1 overexpression promotes cancer development by activating the mTOR-STAT3 and PI3K-AKT signal pathways, suggesting that lncRNA UCA1 may play a critical role in tumorigenesis, invasion, and metastasis." (PMID 31572567, 2019). "In OC tissue and several other cancers, UCA1 is re-activated and overexpressed." (PMID 32039022, 2019). "UCA1 expression was markedly higher in cetuximab-resistant cancer cells and their exosomes." (PMID 30377411, 2018). "In previous reports, UCA1 had been identified as an oncogene in some cancer types." (PMID 29516678, 2018). "Moreover, UCA1 expression level was also evaluated in the cases of GC by interrogating a database containing 407 GC patients from the Cancer Atlas Project (TCGA)." (PMID 30464170, 2018). "In different cancer cells, UCA1 has been demonstrated to bind to several miRNAs." (PMID 30377411, 2018). "In addition to its oncogenic effect, UCA1 also exerts a regulatory effect on drug resistance in several types of cancer." (PMID 30377411, 2018). "In addition to its oncogenic function, UCA1 regulates drug resistance in some kinds of malignant tumors." (PMID 30377411, 2018). "Analysis of UCA1 expression and patient survival data from the TCGA dataset shows that its expression was correlated with increased hazard ratio in different types of cancers, in particular with pancreatic adenocarcinoma." (PMID 30441811, 2018). "The potential of UCA1 in promoting cancer progression has been reported in other cancers." (PMID 30464170, 2018). "UCA1 was reported to interact with 29 miRNAs in several types of cancers." (PMID 30441811, 2018). "These evidences indicate lncRNA UCA1 play an important role during cancer progression." (PMID 30464170, 2018).
cancer (continued). "Thus, its high expression in several carcinomas was an unsurprising observation because UCA1 is frequently overexpressed in cancerous tissues relative to normal tissues." (PMID 29755696, 2018). "LncRNA UCA1 has also been reported to bind to several miRNAs in different cancer cells." (PMID 28969100, 2017). "UCA1 expression regulates cancer cell proliferation, migration, and invasion." (PMID 27902466, 2017). "Although the role of lncRNAs in cancer drug resistance is only beginning to be discovered, the application potential of lncRNA UCA1 as a candidate to develop novel strategies to reverse drug sensitivity to chemotherapy or molecular targeted therapy cannot be ignored." (PMID 28969100, 2017). "Although UCA1 has been found to have a pro-metastatic role in several types of cancers, its pathway and downstream targets remain largely unknown." (PMID 28327194, 2017). "Besides the oncogenic function, lncRNA UCA1 also regulates drug resistance in multiple types of malignant tumors." (PMID 28969100, 2017). "In conclusion, the present meta-analysis demonstrated that high expression of UCA1 might serve as a common molecular marker for predicting lymph node metastasis and prognosis in various cancers." (PMID 27713161, 2017). "However, larger-size, multi-center and higher-quality studies with a unified criterion for determining lncRNA UCA1 expression are necessary to validate and confirm these results for the different kinds of cancers." (PMID 28969100, 2017). "This study aimed to further explore the prognosis role and clinical significance of UCA1 in cancer." (PMID 28423704, 2017). "Among the changed lncRNAs, we focused on UCA1 because it is a cancer-related lncRNA." (PMID 28209917, 2017). "We then determined whether UCA1 affected the functions of gastric BGC-823 cancer cells, using lentivirus UCA1 overexpression and siRNA stably-transfected cells." (PMID 29212166, 2017). "Previous studies have reported that UCA1 played a significant role in various types of cancer." (PMID 28380443, 2017). "All of these results above suggest that high UCA1 expression may be regarded as an unfavorable predictor in different cancers (pooled HR = 1.85, 95% CI 1.62–2.10, p < 0.001)." (PMID 28423704, 2017). "Among the transcripts our microarray data have revealed to be dysregulated, the lncRNA UCA1, which has an oncogenic role in several types of cancer, may help modulate the pathogenesis of HSCC." (PMID 28327194, 2017). "Therefore, we propose that further animal model studies and prospective clinical studies will highlight and describe the role of lncRNA UCA1 in anti-cancer drug resistance leading to its investigation for various clinical applications in the future." (PMID 28969100, 2017). "There was also a significantly negative association between high level of UCA1 and poor grade cancer (pooled OR = 2.74, 95% CI 2.04–3.70, p < 0.001) and positive lymphatic metastasis (pooled OR = 2.43, 95% CI 1.72–3.41, p < 0.001)." (PMID 28423704, 2017). "UCA1 plays an important role in establishing chemoresistance in lung (gefitinib), gastric (adriamycin), breast (tamoxifen), esophagus (cisplatin), and ovarian (cisplatin) cancers." (PMID 29299178, 2017). "UCA1 could serve as a novel biomarker for prognosis and might be a potential predictive factor for clinicopathological characteristics in various cancers." (PMID 27517147, 2016). "This study suggests that the miR-1/UCA1 axis may have potential to be developed as a therapeutic option for this cancer." (PMID 26978351, 2016). "From the pooled results, we could find that increased UCA1 expression was positively correlated with advanced clinical stage, and cancer patients with high UCA1 expression may develop with an increased risk of LNM and DM." (PMID 27517147, 2016). "In conclusion, the results of this meta-analysis suggest that UCA1 may be a risk factor for shorter OS and PFS in cancers." (PMID 27329842, 2016).
cancer (continued). "In addition, upregulation of lncRNA UCA1 was also detected in the tamoxifen-resistant cancer cells compared with their parent cells." (PMID 27977766, 2016). "These demonstrated the function of UCA1 in promoting cancer development." (PMID 27009634, 2016). "Furthermore, many other established, cancer-linked lncRNAs, including HOTAIR, MALAT-1, NEAT-1, and UCA-1, were found to be either extremely lowly expressed (mean and median cpm < 1) or insufficiently dysregulated in HNSCCs." (PMID 27323410, 2016). "Moreover, long non-coding RNAs, like UCA1, are increasingly thought to play a pivotal role in cancer development and progression." (PMID 26191476, 2015). "Thus, areca nut-induced UCA1 in HNC cells may facilitate cancer invasion and progression, leading to worse treatment outcomes." (PMID 36980216, 2023). "However, the UCA1 score can not only distinguish benign tissue from high‐risk cancer well, but can also distinguish benign tissue from nonhigh‐risk cancer." (PMID 35289508, 2022). "Moreover, targeted therapies against lncRNA UCA1 can also be developed for cancer therapy." (PMID 33936199, 2021). "Therefore, UCA1-mediated ceRNA networks are potential targets in preventing cancer progression." (PMID 34733326, 2021). "Indeed, miR-582-5p-mediated suppression of ATG7 could inhibit autophagy, indicating the UCA1/miR-582-5p/ATG7 pathway regulates BC anti-cancer drug response." (PMID 32756406, 2020). "Consequently, it is suggested that UCA1 may promote the metastasis of cancer cells and may be a prognostic indicator of lymph node metastasis in HNSCC." (PMID 33123473, 2020). "Compared to matched normal peritumoral tissues, the UCA1 expression was up-regulated remarkably in 68.2% (60 of 88) of cancer tissues (P = 0.021), and about 2.12 times,and the miR-182-5p expression was down-regulated remarkably in 72.7% (64 of 88) of cancer tissues (P = 0.002)." (PMID 31996265, 2020). "However, the molecular mechanism of UCA1 in cancer progression remains incompletely understood." (PMID 31040354, 2019). "First, UCA1 could act as a key competing endogenous RNA (ceRNA) or sponge for miR-204-5p, miR-193a-3p, miR-145, miR-143, miR-216b, miR-203, miR-196a-5p and miR-135a in several different cancers." (PMID 30918102, 2019). "Thus, UCA1 might be a novel predictive marker for estimating the metastasis and prognosis in different types of cancer." (PMID 30918102, 2019). "Furthermore, many studies have shown that UCA1 induces drug resistance in various cancers." (PMID 30377411, 2018). "Interestingly, UCA1 can also function as a ceRNA in cancer cells by interacting with miRNA." (PMID 27893417, 2017). "Furthermore, increasing interest has been focused on whether UCA1 acts as a diagnosis and prognosis biomarker in cancer detection and treatment." (PMID 28423704, 2017). "Moreover, upregulated UCA1 could promote cancer progression by regulating mTOR or Wnt signaling pathway." (PMID 29221199, 2017). "Thus, the predictive significance of evaluated UCA1 in poor prognosis of patients with cancer might be overestimated to some extent." (PMID 28423704, 2017). "Moreover, the involvement of UCA1 in drug resistance was also disclosed in a variety of cancers." (PMID 29125238, 2017). "Therefore, UCA1 is overexpressed in different cancers and correlates with poor prognosis." (PMID 29033906, 2017). "It suggested that UCA1 could act as an independent prognostic factor for OS in cancer patients." (PMID 27517147, 2016). "Investigations concerning UCA1 and HOTAIR, analogous to those on MALAT1, have primarily concentrated on the downregulation of these lncRNAs and the subsequent diminution in cancer progression." (PMID 40699668, 2025). "Suppressing lncRNAs such as NEAT1, MALAT1, and UCA1 through various methods including CRISPR/Cas9, siRNA, or antisense oligonucleotides has been shown to impede cancer development." (PMID 39941858, 2025).
cancer (continued). "Recent research has highlighted the role of the SE‐lncRNA UCA1 in activating YAP, revealing that dysregulated activation of the YAP/TAZ axis is observed in the tumour microenvironment of several cancers, including lung and breast cancer." (PMID 39690143, 2024). "LUCAT1, UCA1, and MIR31HG were significantly increased in the cancer group (p < 0.05), particularly LUCAT1 and MIR31HG (p < 0.0001)." (PMID 36980216, 2023). "LncRNA UCA1 promotes the stemness and proliferation of cancer cells for escaping from anticancer treatment, where stemness regulators Nanog, ALDH1, and HXK2 expression were regulated by the UCA1/miR-1, miR-203/Slug axis." (PMID 35736633, 2022). "Numerous lncRNAs, such as NEAT1, UCA1, MIR22HG, and LINK-A, have involved in immune regulation in cancer." (PMID 36071454, 2022). "Correlation analysis showed that the expression of UCA1 and WT1-AS were inversely and significantly correlated in both NSCNC tissues and non-cancer tissues." (PMID 33514344, 2021). "The results revealed a higher UCA1 expression level in A549/DDP cells and LUAD tissues than in A549 cells and adjacent cancer tissues." (PMID 34544452, 2021). "UCA1 via modulation of the PI3K–AKT, ERK1/2, and MAPK pathways can regulate the proliferation of cells in various cancers." (PMID 34950142, 2021). "However, how UCA1 is regulated in cancer is largely unknown." (PMID 34809621, 2021). "Previous study reported that upregulated UCA1 promoted programmed death ligand 1 (PDL1) expression through the repression of miRNAs and contributed to immune escape in cancers." (PMID 34124046, 2021). "Consistently, we also showed that upregulation of UCA1 in NSCLC tissues and its enhancing effects on cancer cell invasion and migration." (PMID 33514344, 2021). "Glucose transporters (GLUTs) as important modulators of glucose utilization which are commonly dysregulated in cancer, have been shown to be targeted by several lncRNAs such as LINC01638, Ftx, XIST, YIYA (LINC00538), HISLA, AWPPH, and UCA1." (PMID 33123468, 2020). "Thirty-five cancer-relevant lncRNAs were identified, including the oncogenic lncRNAs MALAT1 and UCA1 and lncRNAs GAS5 and TUG1, which act as tumor suppressors." (PMID 33519750, 2020). "In summary, our study demonstrates that UCA1 plays an important regulator of MMP9 and trophoblast invasion, in addition to its role in the cancer development." (PMID 31572567, 2019). "LncRNAs such as NEAT1, UCA1, and PVT-1 have been shown to regulate drug resistance in multiple cancer types through different molecular mechanisms." (PMID 35582574, 2019). "Some other lncRNAs (UCA1, RP11-458F8.4, RP1-239B22.5, and ALMS1-IT1) that were upregulated in cancers showed a higher expression in the late stage than in the early stage." (PMID 30984308, 2019). "This also holds true for UCA1 regulating mediators of AKT signaling and its downstream targets in diverse cancer cells." (PMID 30441811, 2018). "Several researches have showed that the increased expression of 6 lncRNAs (H19, UCA1, TUG1, MALAT1, SPRY4-IT1, and HOTAIR) was correlated to poor prognostic outcome of cancers, those findings in consist with our results." (PMID 29870555, 2018). "For example, the lncRNAs TUG1, UCA1, SPRY4-IT1, HULC, HOTTIP, H19 and HOTAIR were found to be novel promising biomarkers for poor prognosis in human cancers." (PMID 29308050, 2018). "Thus, we wonder whether the TGF‐β–UCA1–Slug regulatory axis is a common phenomenon in cancers." (PMID 30410864, 2018). "LncRNAs, including UCA1, were shown to bind to Brahma related gene 1 (BRG1) in a variety of cancer cells, while others bind to SNF5 and BAF200a of these SWI/SNF complexes." (PMID 30441811, 2018). "In addition, the higher expression of UCA1 could be detected in the serum of patient with cancer, which suggested that it may be a superior biomarker among current protein-coding biomarkers for cancer diagnostics and prognosis evaluation." (PMID 30464170, 2018).
cancer (continued). "As a lncRNA dysregulated in TSCC, UCA1 is closely related to its LNM, and its silencing markedly dampens cancer invasiveness." (PMID 29368602, 2018). "Using this approach with different cancer types, oncogenic lncRNAs such as MALAT-1, ANRIL, UCA1, and tumor suppressor lncRNAs like Gas-5 and MEG3 have been functionally characterized." (PMID 28715488, 2017). "To understand the mechanisms by which cancer-related lncRNAs are deregulated by KSHV, and their contribution to pathogenesis, we chose to initially study UCA1, ANRIL and MEG3." (PMID 28715488, 2017). "In conclusion, the meta-analysis offers evidence that up-regulated UCA1 is significantly corrected with LNM and poor OS in patients with various cancers." (PMID 27713161, 2017). "The authors went on to show that overexpression of UCA1 and GLS2 resulted in decreased production of radical oxygen species in cancer cells, perhaps further augmenting their survival capabilities." (PMID 26978351, 2016). "In conclusion, this meta-analysis indicated that higher levels of UCA1 correlate with shorter PFS and OS times in cancers." (PMID 27329842, 2016). "Mining the pathways regulated by UCA1 and CAPERα/TBX3 will reveal factors that control cell proliferation and fate during development and disease and thus constitute novel cancer therapeutic targets." (PMID 24876127, 2014). "The ME180 mouse xenograft models exhibited a decrease in cancer development following the silencing of UCA1, while demonstrating a negative correlation between UCA1 and SMARCD3." (PMID 38534790, 2024). "In addition, metformin action on other types of cancers by regulating ten lncRNAs including AC006160.1, Loc100506691, lncRNA-AF085935, SNHG7, HULC, UCA1, H19, MALAT1, AFAP1-AS1, AC026904.1 is described." (PMID 36849958, 2023). "Especially in gastric cancer cells, lncRNA UCA1 promotes the upregulation of CYP1B1 (cytochrome P450 family 1 subfamily B member 1) through sponging miR-513a-3p, resulting in cisplatin resistance and cancer cell proliferation." (PMID 36499136, 2022). "Additional evidence showed that UCA1 promotes cell migration due to its ability to inhibit miR-7-5p, thereby enhancing the level of epidermal growth factor receptor (EGFR) in hypoxia-resistant cancer cells." (PMID 34298879, 2021). "Therefore, lncRNAs, such as MALAT1, UBE2CP3, HULC, UCA1, and PCA3 play an essential role in cancer metastasis by altering gene expression." (PMID 33805687, 2021). "Also, both lncRNA UCA1 and CLIC1 promoted the phosphorylation of ERK and mitogen-activated protein kinase (MAPK), activating ERK/MAPK signaling pathway to promote cancer cell metastasis." (PMID 33936199, 2021). "Several lncRNAs have been linked to various types of cancer; for example, terminal differentiation-induced non-coding RNA (TINCR), lncRNA-p21, lncRNA OIP5-AS1, lncRNA UCA1 and Hox transcript antisense intergenic RNA (HOTAIR) have been identified as potential therapeutic targets for cancer treatment." (PMID 34868956, 2021). "Oppositely, UCA1-induced Hippo-YAP activation could suppress autophagy and exacerbate cancer process." (PMID 32278350, 2020). "UCA1 is highly expressed in numerous cancers, including non-small cell lung cancer, gastric cancer and ovarian cancer." (PMID 33680939, 2020). "The results demonstrated that high expression of UCA1 might accelerate the progression of EMS, which is consistent with its changes in various malignant tumors." (PMID 33680939, 2020). "The results showed that GAS8-AS1 was downregulated, while UCA1 was upregulate in cancer tissues in comparison to adjacent non-cancer tissues of OS patients." (PMID 32013985, 2020). "“Cancer stem cell”, “HOTAIR” and “UCA1” were the frontiers of the fields in recent years." (PMID 31143372, 2019). "Nevertheless, some studies showed no statistical impact of UCA1 dysregulation on cancer metastasis and prognosis." (PMID 30918102, 2019). "The first 3 burst words after 2014 were “cancer stem cell”, “HOTAIR” and “UCA1”." (PMID 31143372, 2019).